GOLGA8A (golgin A8 family member A)
Description:
May be involved in maintaining Golgi structure.
Synonyms: GM88; GOLGIN-67; FAP286; CFAP286
Tractability: Antibody: UniProt places it where antibodies can reach, with medium confidence. PROTAC: ubiquitination databases record sites on it.
Gene: Protein-coding gene on chromosome 15 (34,378,935 to 34,437,851, reverse strand). Ensembl gene ENSG00000175265.
Subcellular location: Golgi apparatus, Golgi stack membrane
Subcellular location (Human Protein Atlas): Golgi apparatus; Cytosol
Gene Ontology:
Biological process: Golgi organization
Cellular component: cis-Golgi network; Golgi cis cisterna; Golgi cisterna membrane; Golgi apparatus
Genetic constraint (gnomAD): Loss-of-function variants: 2 observed, 5.64 expected, observed/expected ratio (o/e) 0.35, 90% interval 0.14 to 1.11. That is too few expected variants to judge how well the gene tolerates losing a copy. Missense variants: 14 observed, 62.46 expected, observed/expected ratio (o/e) 0.22, 90% interval 0.15 to 0.35. Synonymous variants: 6 observed, 22.42 expected, observed/expected ratio (o/e) 0.27, 90% interval 0.15 to 0.53.
Homologues: Orthologues: mouse Golga2 (43% identical), dog GOLGA2 (42% identical), tropical clawed frog golga2 (32% identical), zebrafish golga2 (30% identical), Drosophila melanogaster GM130 (22% identical), Caenorhabditis elegans golg-2 (18% identical), rat Golga2l1 (5% identical). Paralogues in human: GOLGA8B (99% identical), GOLGA8F (76% identical), GOLGA8G (76% identical), GOLGA8S (73% identical), GOLGA8M (70% identical), GOLGA8H (69% identical), GOLGA8J (69% identical), GOLGA8N (69% identical), GOLGA8O (69% identical), GOLGA8Q (69% identical), GOLGA8T (69% identical), GOLGA8K (69% identical), and 6 more.
Diseases named in the same sentence as GOLGA8A in open-access papers:
GOLGA8A is named in the same sentence as 5 diseases in open-access papers, as found by Europe PMC text mining. Sharing a sentence is not in itself a finding about the gene and the disease. The quoted sentences say what the papers report.
intracerebral hemorrhage (1 paper, 2023). A cerebrovascular disorder characterized by bleeding into one or both cerebral hemispheres including the basal ganglia and the cerebral cortex. "So, the GAS6-AS1/hsa-miR-363-3p/GOLGA8A axis in our ceRNA network seems to be related to intracerebral hemorrhage." (PMID 36894947, 2023). "GOLGA8A, one of the target mRNAs of GAS6-AS1 in our ceRNA network, has been shown to be related to intracerebral hemorrhage too." (PMID 36894947, 2023).
pancreatic ductal adenocarcinoma (1 paper, 2020). An infiltrating adenocarcinoma that arises from the epithelial cells of the pancreas. "Significant biallelic deletions of GOLGA8A have been described in gastrointestinal tumors and pancreatic ductal adenocarcinomas." (PMID 32577795, 2020).
GOLGA8A also shares sentences with these, for which no sentence is quoted: frontotemporal lobar degeneration (1 paper); gastrointestinal tumors (1); liver cancer (1).